SIRPA (signal regulatory protein alpha)
Diseases named in the same sentence as SIRPA in open-access papers (continued):
Sharing a sentence is not in itself a finding about the gene and the disease.
cancer (continued). "Signal regulatory protein alpha (SIRPα) on TAMs interacts with CD47, a “don't eat me” signal on cancer cells, preventing the phagocytosis of macrophages for cancer cells." (PMID 35585567, 2022). "DSP107 assembles into a natural homotrimer due to the 4-1BBL trimerization domain and, upon binding to CD47 on cancer cells, breaks the CD47:SIRPα interaction." (PMID 35287686, 2022). "In vitro cytotoxicity assays ascertained the high cytotoxicity of Sirpα−/− BMDM-expanded Tc, which induced rapid cancer cell death at low effector: target ratios (1–3:1)." (PMID 34050181, 2021). "Our research provides a promising candidate for cancer immunotherapy, bridging the innate and adaptive immunity by a CD47/SIRPα and TIGIT/PVR blockade." (PMID 34068552, 2021). "Combined with SIRPα on the surface of macrophages, CD47 on the surface of cancer cells can send an antiphagocytic “Don’t eat me” signal to the immune system that helps to avoid immune surveillance." (PMID 34805154, 2021). "Because the effect of CD47 antagonists for cancer treatment requires blocking CD47 and SIRPα interaction, we examined CD47 expression on selected cells." (PMID 33629544, 2021). "Cancer cells express CD47 to protect cells from phagocytosis by binding and activating the receptor SIRPα on macrophages to inhibit macrophage phagocytosis." (PMID 34717710, 2021). "The crosstalk between the cancer cell CD47 and the macrophage signal-regulatory protein alpha (SIRPα) has been designated as the innate immune checkpoint." (PMID 34575416, 2021). "In this study, it shows that the formation of pyroglutamate on CD47 enhances the binding of SIRPα to CD47, consequently, inhibits cancer cell clearance by phagocytes." (PMID 34512146, 2021). "In contrast to the restricted expression of SIRPα, CD47 is expressed on both healthy and cancer cells." (PMID 34717705, 2021). "Some researchers have synthesized responsive exosomes nano-bioconjugates for cancer therapy, which coupled the azide-modified exosomes derived from M1 with dibenzocyclooctyne-modified antibodies of CD47 and SIRPα." (PMID 34625124, 2021). "In this article, we review the role of CD47/SIRPα axis in cancer, and summarize the literature on the efficacy and safety of therapeutics targeting CD47 or SIRPα." (PMID 34944850, 2021). "Afterwards, we explored alterations in SIRPα levels in the phagocytic macrophages, those engulfing CFSE+ cancer cells (CD14+CFSE+)." (PMID 32231135, 2020). "Similar to cancers, there is growing evidence that the inhibition of CD47/SIRPa interaction induces an antimicrobial effect during infections." (PMID 32882841, 2020). "Based on these results, we further analyzed the SIRPα expression in macrophages and CD47 in cancer cells from the indirect co-cultures, maintained for 72 h at 20% or 1% O2, before the direct contact with the CFSE-labeled cancer cells." (PMID 32231135, 2020). "M2-conditioned medium induces CD47 expression in cancer cells, and M2 macrophages express more SIRPα and migrate to CD47+ cells faster, while CD47+ cancer cells invade more quickly in the presence of M2 macrophages." (PMID 35582455, 2020). "Noteworthy, it is known that cancer cells express “don’t eat me” signals, as the CD47 receptor, which will bind to SIRPα in macrophages, and impairs phagocytosis." (PMID 32231135, 2020). "Hu5F9-G4 also blocked the binding of SIRPα on the surface of lymphoma cells to CD47 on the surface of macrophages, thus attenuating the “don't eat me” signals within this cancer cell type." (PMID 32082311, 2020). "Activation of CD47 in T cells mainly leads to the suppression of their immune response, while the interaction of CD47 with SIRPα or TSP-1 induces proliferation and activation of antigen-specific T cells, thereby improving the immune response to cancer cells." (PMID 32733941, 2020). "In particular, cancer cells express CD47, a ‘don’t eat me’ signal that interacts with signal regulatory protein alpha (SIRPα) on macrophages to prevent phagocytosis." (PMID 32999291, 2020).
cancer (continued). "In many cancer types, CD47 binding to signal-regulatory protein α (SIRPα) initiates an inhibitory signaling pathway that leads to the evasion of malignant cells from phagocytosis by macrophages." (PMID 32082311, 2020). "Participating in the bidirectional inhibitory signaling through both CD47 and its ligand SIRPα on macrophages, CD47 has been regarded as the first gene known to be a target for cancer immunotherapy common to all types of cancers." (PMID 31139022, 2019). "Preventing the binding between SIRPα and CD47 by B6H12 antibodies enhances cancer cell killing by immune cells." (PMID 30814491, 2019). "By inducing inhibitory SIRPα signaling, elevated CD47 expression by some cancers prevents macrophage phagocytosis." (PMID 26840086, 2016). "One of the most promising antibody-mediated therapeutic strategies to date is based on inhibiting the interaction between SIRPα and CD47, a transmembrane protein expressed on many cancer cells and CSCs, to allow for increased phagocytosis of cancer cells." (PMID 26980947, 2016). "Another similarity is that both SIRPα and CD200R interactions are the subject of interest as possible therapeutics especially for cancer." (PMID 23691022, 2013). "Our in vitro studies demonstrated that 1B2–10 effectively disrupted the interaction between CD47 and SIRPα, thereby abrogating the “don’t eat me” signal and resulting in a significant enhancement of macrophage-mediated phagocytosis against CD47-expressing cancer cell lines." (PMID 41383500, 2025). "The effects of MY-1 differ between tumors with and without SIRPα expression, indicating that endogenous SIRPα in cancer cells is involved in certain regulatory mechanisms." (PMID 40589735, 2025). "SIRPα is widely studied as an inhibitory receptor on macrophages, which recognizes as a ligand of the cell surface molecule CD47, expressed mainly on myeloid cells and also upregulated on cancer cells." (PMID 40523887, 2025). "Since our anti-SIRPα antibodies are capable of blocking the SIRPα/CD47 interaction, we next sought to assess whether our antibodies can restore and enhance macrophage phagocytic activity against cancer cells." (PMID 40136470, 2025). "Additionally, the DSPE-PEG2000-Mal-RS17 peptide (RS17 peptide), a peptide with antitumor properties, targets CD47 in cancer cells, inhibits the CD47–signal regulatory protein alpha (SIRPα) signaling pathway, and increases macrophage engulfment." (PMID 40051791, 2025). "Although the absence of costimulatory signals prevents the direct activation of T cells, our study revealed that MHC-II+ cancer cells exhibit upregulated CD47 expression, which enhances their interaction with SIRPα on macrophages and transmits a "don't eat me" signal that inhibits phagocytosis." (PMID 41281745, 2025). "CD47, also known as “do not eat me” signal, prevents the phagocytosis of cancer cells by interacting with signal regulatory protein alpha (SIRPα) on macrophages or other myeloid cells, preventing the cytoskeletal rearrangement needed for phagocytosis." (PMID 38414061, 2024). "IMM0306 activates macrophages and NK cells by blocking the connection between CD47 and SIRPα and engaging FcγR, resulting in excellent cancer-killing effectiveness without binding activity on human RBCs and no hemolytic side effects." (PMID 39040441, 2024). "Single-cell RNA-seq analysis of a primary BC sample, focusing on examining the expression patterns of CD47, CD24, CD274, SIRPα and Siglec-10 at the individual cell level, revealed a prominent expression of CD47 and CD24 in cancer cells, notably higher than that of CD274." (PMID 38971872, 2024). "Elevated expression of CD47 is observed in a wide range of cancer cells as a mechanism for evading the immune system, blocking the interaction between the CD47 and SIRPα is the most advanced and promising therapeutic approach currently investigated in multiple clinical trials." (PMID 38426113, 2024).
cancer (continued). "CD47 serves as a “do not eat me” signaling checkpoint, facilitating cancer cells to evade macrophage-mediated phagocytosis through its interaction with signal-regulatory protein alpha (SIRPα)." (PMID 38185685, 2024). "SIRPα recognizes the ligand CD47, which is often overexpressed in cancer cells." (PMID 40458305, 2024). "In addition, exosomal ZEB1 derived from hypoxic CSCC cells promotes SIRPα+ TAM polarization via activation of the STAT3 signalling pathway and thus facilitates immune evasion by cancer cells." (PMID 38183060, 2024). "Binding to CD47 triggers inhibitory signaling through SIRPα that prevents macrophage phagocytosis of nonmalignant and cancer cells." (PMID 38495618, 2024). "The CD47-SIRPα pathway is a “do not eat me” signal expressed by several cancers, including cHL, which leads to the avoidance of phagocytosis through interaction with Signal-Regulatory Protein alpha (SIRPα) expressed on TAMs and other phagocytes." (PMID 38791909, 2024). "Similarly, for SIRPA, a significant correlation with RPN1 expression was found in 12 cancer types (r > 0.2, P < 0.05)." (PMID 39749324, 2024). "Since the SIRPα–CD47 protein complex has been recognized as a promising therapeutic target in cancer, our detailed studies on the cooperative binding of CD47 to SIRPα may have an influence on the advancement of new cancer treatments." (PMID 37999357, 2023). "Also, the interaction of SIRPα on macrophages and CD47 on cancer cells inhibits the clearance of cancer cells via phagocytosis." (PMID 38111068, 2023). "Like T-cells, macrophages, members of the innate immune system, are also known to express a checkpoint receptor known as signal regulatory protein a (SIRPα or CD172α), which attaches to its ligand CD47, a transmembrane protein overexpressed by cancer cells, including myeloma cells." (PMID 37958658, 2023). "It is also reasonable to speculate that the combination of KRAS inhibitors and immune checkpoint inhibitors, including inhibitors of PD-1/PD-L1 or CD47/SIRPα, could provide synergistic benefits to patients with KRAS-driven cancers." (PMID 36413402, 2023). "Third approach of TAM reprogramming is to promote antigen presentation and phagocytosis of TAMs by blocking anti-phagocytic surface proteins called “don’t eat me” signals, like SIRPα or Siglec-10, with antibodies blocking CD47 or CD24 expressed on cancer cells." (PMID 35211124, 2022). "However, neutrophils prominently express the myeloid inhibitory receptor SIRPα, which upon interaction with the ‘don’t eat me’ signal CD47 on cancer cells, limits cytotoxicity, forming a mechanism of resistance towards anti-cancer antibody therapeutics." (PMID 35884427, 2022). "Cancer cells can evade macrophage-mediated phagocytosis by upregulating cell-surface expression of “don’t eat me signals”, such as CD47, PD-L1, β2M, and CD24, which bind to the phagocytosis-inhibiting receptors SIRPα, PD-1, LILRB1 and Siglec-10, respectively." (PMID 36347876, 2022). "In addition, cancers escape ADCP and ADCC by expressing CD47 on the plasma membrane to bind to SIRPα-expressing TAMs to inhibit these anti-cancer mechanisms." (PMID 36077152, 2022). "We further compared ZL-1201 with the benchmark in a variety of preclinical in vitro studies, and the data showed that ZL-1201 binds CD47 on multiple cancer cells, RBCs, and platelets, and blocks the interaction between CD47 and SIRPα with potency similar to that of the benchmark." (PMID 36970051, 2022). "The cluster of differentiation 47 (CD47) protein, expressed on both healthy and cancer cells, plays a pivotal role in this balance by delivering a “do not eat me signal” upon binding to the signal-regulatory protein alpha (SIRPα) receptor on myeloid cells." (PMID 36080360, 2022). "CD47 is a strong ‘do not eat me’ signal that helps cancer cells to escape the recognition and the destruction by macrophages expressing signal regulatory protein alpha (SIRPα)." (PMID 35626032, 2022).
cancer (continued). "In addition, we found that macrophage subpopulations (clusters 1, 5, 7, 8, and 9) from cancer tissues expressed a certain number of immunosuppressive genes, such as VEGFA, MMP14, MMP19, S100A2, APOE, HMOX1, SLAMF7, SIRPα, LAG3 and IL18." (PMID 36158683, 2022). "For instance, CD47 is known to orchestrate a protective mechanism by which both (cancer) cells and EVs evade phagocytosis as it interacts with its receptor signal regulatory protein alpha (SIRPα) present on immune cells to trigger a “do not eat me” signal." (PMID 35214000, 2022). "In the in vitro experiments above, surface-exposed CD47 on cancer cells binds with a monoclonal antibody (B6H12.2), whereas in the body, CD47 would bind with SIRPα, an immune receptor found on macrophages, dendritic cells, and other cells of the innate immune system." (PMID 33540720, 2021). "Noteworthily, the expression of SIRPα, SIGLEC10, and LILRB1 also increased in cancer tissues." (PMID 34778091, 2021). "Besides, in combination with SIRPα on the surface of macrophages, CD47 can send an antiphagocytic “Don’t eat me” signal to the immune system that helps cancer cells avoid immune surveillance." (PMID 34805154, 2021). "The “do not eat me” signal CD47, overexpressed on the surface of cancer cells, forms a signaling complex with signal-regulatory protein α (SIRPα), a myeloid-specific immune checkpoint, enabling the escape from macrophage-mediated phagocytosis." (PMID 34683963, 2021). "Dual-target small molecule inhibitor (SMI) co-targeting the CD47/SIRPα and TIGIT/PVR may also exert exciting effects in the cancer immunotherapy." (PMID 34068552, 2021). "Interestingly, “don’t eat-me signal” CD47 on cancer cells inhibits neutrophil trogoptosis via interaction with signal regulatory protein a (SIRPa), which provides mechanistic insight into the CD47-SIRPa checkpoint blockade." (PMID 34069602, 2021). "Indeed, the dual signaling protein SIRPα-4-1BB blocked the interaction of SIRPα with CD47 and induced in vitro neutrophil- and macrophage-mediated phagocytosis of cancer cells." (PMID 33105656, 2020). "Here, a novel oncolytic adenovirus carrying a signal regulatory protein‐α (SIRPα)‐IgG1 Fc fusion gene (termed SG635‐SF) was constructed, which could block the CD47 ‘don't eat me’ signal of cancer cells." (PMID 31899582, 2020). "Engineered exosomes that antagonize the interaction between CD47 and SIRPα promote intensive T cell infiltration in syngeneic mouse models of cancer, indicating that exosome-mediated immunotherapy targeting the CD47/SIRPα axis is one of the most promising new strategies for immuno-oncology." (PMID 33168028, 2020). "CD47 is expressed on cancer cells, which can bind to SIRPα on macrophages and serve as a “do not eat me” signal usually presented by normal blood cells; it enables cancer cells to evade immunosurveillance by macrophages or other phagocytes." (PMID 31655607, 2019). "Furthermore, anti-SIRPα antibodies (e.g., KWAR23) were also found to help macrophages to diminish cancer progression and metastasis." (PMID 31575023, 2019). "We then examined whether ZF1 could functionally block the interaction between CD47 and SIRPα, which were known to inhibit macrophage-mediated phagocytosis of CD47+ cancer cells." (PMID 27863402, 2016). "Cancer cells could escape phagocytosis via CD47 overexpression, which in turn signaling to macrophage via binding SIRPα on cell surface." (PMID 27863402, 2016). "Accordingly, the monoclonal antibody blockade against SIRPα could offer new treatment options for cancer by restoring macrophage-mediated phagocytosis without side effects associated with targeting CD47 directly." (PMID 40136470, 2025). "Clinical trials of targeted neutrophil therapies for cancers aim to evaluate the safety, efficacy, and biological impact of novel interventions targeting key molecular pathways such as CXCR1/CXCR2, STAT3, IL-6, TGF-β, and Cluster of Differentiation 47—Signal Regulatory Protein Alpha (CD47-SIRPα)." (PMID 40227814, 2025).
cancer (continued). "In addition, CD47 is also crucial for cancer cells to evade immune clearance, and abolishing the binding of CD47 to SIRPα could induce target cell phagocytosis by macrophages." (PMID 38981064, 2024). "In addition, considerable infiltration of CD163+ TAMs and SIRPα+ TAMs were observed in the stroma surrounding the hypoxic cancer cell islets but not in the normoxic regions." (PMID 38183060, 2024). "Finally, TNFSF10—TNFRSF10B (TRIAL—TRIAL-R), SIRPA—CD47 (“don't eat me”), C5AR1—RPS19, and GAS6—AXL act as negative regulators of the innate immune system by inhibiting cytokine responses, phagocytosis of cancer cells, and promoting the immunosuppressive TME." (PMID 37823774, 2023). "Moreover, the clearance of cancer cells by macrophages was also suppressed following psychological stress via disturbing the balance of the “eat me” signal receptor LRP1 and “don’t eat me” signal SIRPα on macrophages." (PMID 37210553, 2023). "However, the effects of targeting SIRPα on cancer immunotherapy have not been well investigated so far." (PMID 36419386, 2023). "Therefore, we tested whether CRISPR-Cas9 mediated SIRPA gene knockout in monocytes can enhance ADCP and ADCC against a rituximab-opsonized CD47-expressing cancer cell line, i.e., Raji cells." (PMID 36077152, 2022). "In line with this hypothesis, exosomes loaded with SIRPα induced phagocytosis of cancer cells up to 30% without a requirement for Fc, a level similar to that obtained in experiments with DSP107." (PMID 35287686, 2022). "In line with this, when activated, bone marrow-derived macrophage (BMDMs) obtained from Sirpα−/− mice displayed a strong capacity to phagocytize CD47-expressing MC38 cancer cells, whereas BMDMs from WT mice failed to engulf cancer cells under the same treatment." (PMID 34050181, 2021). "Furthermore, in cancers resistant to CD47 blockade, anti-CD24 mAb enhance the phagocytic ability of macrophages, indicating there is a synergistic effect between CD24 interference and anti-CD47/SIRPα treatment." (PMID 34625124, 2021). "In addition, Mo-TAMs expressed SIRPA and showed a selective upregulation of PD1 and leukocyte immunoglobulin-like receptor LILRB1, two additional inhibitory receptors impairing macrophage-dependent clearance of cancer cells." (PMID 33922336, 2021). "Interactions between SIRPα on phagocytic cells and CD47 on phagocytosed targets, such as erythrocytes, cancer cells, and apoptotic cells, act as a ‘don’t eat me’ signal and thereby control erythrocyte homeostasis, elimination of cancer cells, and the formation of arteriosclerotic plaques." (PMID 30910011, 2019). "In 2015, as part of the Reproducibility Project: Cancer Biology, we published a Registered Report that described how we intended to replicate selected experiments from the paper “The CD47-signal regulatory protein alpha (SIRPa) interaction is a therapeutic target for human solid tumors “." (PMID 28100392, 2017). "Our data support the usage of PPRHs to diminish CD47/SIRPα interaction by decreasing the expression of both molecules thus resulting in an enhanced killing of MCF-7 cells by macrophages, which might translate into beneficial effects in cancer therapy." (PMID 27671753, 2016). "Importantly, PSFL‐NK13 did not affect the expression of SIRPα protein on macrophage membranes (control vs 4 μm PSFL‐NK13, p = 0.3992), reinforcing its specificity for CD47/αvβ3 interactions on cancer cell membranes without impacting SIRPα on macrophage membranes." (PMID 41168993, 2026). "In addition to block CD47/SIRPα checkpoint alone, combined SIRPα/CD47 with PD-1/PD-L1 blockade enhances the efficiency of antitumor immunotherapy 41, 47, 48, suggesting that SIRPα-CD47 axis blockade could enhance PD-1/PD-L1 blockade therapy for cancer." (PMID 34512146, 2021). "The investigational bi-functional fusion protein, SL-172154 (known as SIRPα-Fc-CD40L), is another immunomodulatory agent that operates by blocking the “do not eat me” signal on cancer cells (CD47/SIRPα)." (PMID 41463019, 2025).